PGK1 (phosphoglycerate kinase 1)
Diseases named in the same sentence as PGK1 in open-access papers (continued):
Sharing a sentence is not in itself a finding about the gene and the disease.
tumor (continued). "The second module (M2) was composed of multiple metabolism-relevant phosphoproteins like PGK1, PSMF1, PRDX1, and TOM1, they showed lower expressions in the tumor tissues, especially the high RR tumor tissues." (PMID 38609408, 2024). "In fact, it has been shown for the CPTAC patient cohort that PGK1 and PKM have increased phosphorylation when comparing tumour versus normal." (PMID 39633487, 2024). "The subcutaneous xenograft tumor model and metastasis models confirmed the reversal of the inhibitory effects of TRIM50 on GC growth and metastasis by restoring PGK1 expression." (PMID 38993561, 2024). "In human NSCLC tumor samples, FTSJ1 expression was negatively correlated with PGK1 expression level and the SUVmax value of PET/CT scan." (PMID 39695074, 2024). "Studies have illustrated that O-GlcNAcylation of PGK1 at T255 activates its kinase activity and induces PGK1 translocation into mitochondria, thereby coordinating glycolysis and the TCA cycle to promote tumor development via PGK1-mediated PDH phosphorylation." (PMID 36755301, 2023). "In the Fudan cohort, aberrant glycolysis and alterations in its key enzyme, PGK1, which was negatively correlated with overall survival rate, were noticed at the multi-omics level, and promoted ESCC cell proliferation and tumor growth." (PMID 36966136, 2023). "Therefore, further research on more types of cancer and the high levels of PGK1 in/out of cells is needed to determine whether PGK1 is an inhibitor or activator of tumours, and these studies will support the accurate use of PGK1 therapy in the treatment of cancer." (PMID 37723547, 2023). "In tumor cells, the decreased protein phosphatase activity of PTEN promotes PGK1 Y324 autophosphorylation, glycolysis, and cellular proliferation." (PMID 37226192, 2023). "Among these are the SET domain-containing 5 (Setd5) promoter 43, the Phosphoglucokinase (Pgk1) promoter 44, which are also from the PDGFB-driven tumor and normal comparison, displaying clear differences between the tumors." (PMID 37739938, 2023). "GPI1, TPI1, GAPDH, PGK1, and PKM2 were consistently upregulated in almost all tumor types, while PCK1, PCK2, and FBP1 were downregulated in tumors." (PMID 35246510, 2022). "Accordingly PRAS40 is a downstream factor of PGK1, and PGK1 phosphorylates PRAS40 to promote tumor cell proliferation." (PMID 35058442, 2022). "In conclusion, PGK1-invovled metabolic reprogramming and activation of CXCR4/ERK signaling pathway contributes to tumor growth and sorafenib resistance of KIRC." (PMID 35121728, 2022). "Activation of HIF-1 triggers a panel of down-stream genes (GLUT1, PGK1, HK2, PGM, LDHA and MCT4), and mediates tumor proliferation, angiogenesis, metastasis, cell invasion, migration and glucose metabolism, showing consistency with our results." (PMID 35927239, 2022). "It was consistent that the expression levels of PGK1, CXCR4, p-AKT, p-ERK in xenograft tumor tissues were increased in 786-O-PGK1 group compared with the 786-O-NC group." (PMID 35121728, 2022). "The expression levels of key glycolytic enzymes, namely GLUT1, ENO1, PGK1, ALDOA, HK1, and LDHA, in the tumor tissues of chemotherapy-resistant and chemotherapy-sensitive groups were examined using IHC analysis." (PMID 34510316, 2022). "It targeted ALDO, LDHA, ENO1, PGK1, CA9, and other genes in the invasive tumor and the hypoxic tumor." (PMID 36685583, 2022). "We aslo analyzed the differential expression of PGK1, SDHC, PFKL, and NUP43 in tumor and normal samples." (PMID 33584825, 2021). "Analysis PGK1 expression using the TNM plot analysis showed that PGK1 expression is higher in metastatic tissues than normal and tumor tissues from gene chip data and RNA-seq data (p = 3.78e–33, p = 6.84e–67)." (PMID 34291087, 2021). "The results showed that CACNA1H, IL13RA1, NUP43, PGK1, and SDC1 were highly expressed in tumor samples, while expression of AK3 was significantly decreased." (PMID 34600547, 2021).
tumor (continued). "To date, numerous PGK1 blockers, such as CBR-470-1, NG52, and GQQ-792, have been developed as potential anti-cancer drugs with inhibitory mechanisms on tumor growth, metastasis, the epithelial–mesenchymal transition process, as well as chemotherapy resistance." (PMID 34445528, 2021). "circAGFG1 silencing also reduced the protein expression of HIF-1α and glycolysis-related markers (GLUT1, PGK1, and PKM2) in tumor tissues." (PMID 34013042, 2021). "Through a multi-factor weighted model enrolling the array results, cell validation, expression rates in CTCs and metastasis-related functions reported by literature, PGK1 and G6PD were determined the optimal metabolic markers related to tumor metastasis." (PMID 32028979, 2020). "In vivo experiments using xenograft models revealed that stable over-expression of MZF1 promoted the tumorigenecity of SH-SY5Y cells, as displayed by increase in tumor growth, tumor weight, Ki-67 proliferative index, and elevated levels of HK2 and PGK1." (PMID 32042322, 2020). "PGK1 and G6PD were found closely correlated with the metastatic potential of tumor cells, and CTCs from prostate cancer patients presented heterogeneous expression of these genes." (PMID 32028979, 2020). "Increased expression of PGK1 and G6PD, as critical regulators involved in glycolysis and the pentose phosphate pathway, respectively, reveals active glucose metabolism of tumor cells." (PMID 32028979, 2020). "PGK1 was next shown to interact directly with HSP90 and exhibit pro-tumor effects by modulating the ATPase activity of HSP90." (PMID 30925862, 2019). "To compare PGK1 and PGK2 mRNA levels between tumor and normal tissues, we analyzed the RNA-Seq data of 11,908 tumor cases with 1582 paired normal tissues across 34 cancer types from TCGA datasets." (PMID 31578148, 2019). "We demonstrated a relationship between PGK1 promoter methylation and PGK1 mRNA level and demonstrated the significance of PGK1 mRNA level, PGK1 promoter methylation, and PGK1 pS203 and PDHK1 pT338 levels in tumor progression and cancer patient survival." (PMID 31578148, 2019). "Mitochondrial translocated PGK1 functions as a protein kinase, coordinating glycolysis and the TCA cycle in tumorigenesis and acting in tumor angiogenesis as a disulphide reductase." (PMID 29285267, 2017). "We found well-segregated tumor—clusters representing high and low HIF-1α/PGK1-expressors which accounted for differential expression of Notch signaling genes." (PMID 25734817, 2015). "PGK1 expression is significantly positively correlated with CXCR4 expression and tumor dissemination to the bone marrow." (PMID 24376734, 2013). "A common increase in protein expression in tumor tissues occurred for MnSOD, HMG-1 and PGK-1, whereas a common decrease in tumor tissues occurred for FOV, GST and AST." (PMID 17187689, 2006). "The tumour had been induced in a female backcross CBA mouse heterozygous for the A and B alloenzymes of phosphoglycerate kinase-1 (PGK-1)." (PMID 6197985, 1984). "This patient’s tumor metabolism suggests an adaptive survival program, boosting glycolytic flux via PKM and PGK1 to meet energetic and biosynthetic demands, while downregulating ribosomal machinery to conserve resources, potentially in an mTOR-influenced and immune-suppressive context." (PMID 41367869, 2025). "We demonstrated that TRIM8 stabilizes PGK1 through K63 ubiquitination and recruits ACAT1, driving PGK1 acetylation, thereby enhancing PGK1-mediated glycolysis and ultimately leading to lactate accumulation and tumor angiogenesis." (PMID 41184227, 2025). "Metabolic reprogramming targeting the glycolytic pathway, including targets such as PGK1 and PDHK1, may be a promising approach for ICI-induced cardiotoxicity while retaining anti-tumor efficacy." (PMID 40356915, 2025). "Several groundbreaking studies have confirmed PGK1’s roles in tumor initiation and progression through various non-canonical pathways." (PMID 41213904, 2025).
tumor (continued). "Furthermore, PGK1 may also contribute to tumor progression by influencing the tumor microenvironment, For example, PGK1 could affect the production of extracellular matrix components or modulate the activity of matrix metalloproteinases, which are involved in tumor invasion and metastasis." (PMID 40771921, 2025). "Besides, SMAD4 deficiency induces the upregulation of the glycolytic enzyme PGK1 in PDAC, which enhances tumor glycolytic activity and influences tumor progression and invasion." (PMID 40619414, 2025). "Moreover, we found large tumour size, high T stage, high nodal stage, poor differentiation and high TNM stage were significantly correlated with high PGK1 expression in those ESCC patients." (PMID 40534132, 2025). "ACT001, exerted anti‐tumor activity, inhibited lactate production and promoted anti‐tumor immunity by targeting PGK1, showing no observable systemic toxicity in vivo." (PMID 40016971, 2025). "Genes involved in glycolysis (ALDOA, LDHA, PGK1, PFKL, PGM1) and other metabolic processes (GPX4, PRDX4, ACO2, ASPH, IDH2, SQLE, NPC2, SPTSSA) were upregulated in primary tumor cells, suggesting that the metabolism in primary tumors was distinct from that in their matched metastasis." (PMID 39225101, 2024). "Our qRT‐PCR experiments further revealed that METTL3 may promote the glycolysis capacity of ESCA cells by upregulating the expression of glycolysis‐related genes SLC2A1, GPI, PFKL, PGK1, ENO1 and PKM, thus facilitating tumour cell proliferation and migration." (PMID 38429907, 2024). "Subsequently, protein semiquantification analysis of 24 tumor tissues demonstrated a negative correlation between the expression of PGK1 protein and TRIM50 protein." (PMID 38993561, 2024). "The observation of decreased acetylation in key glycolytic enzymes following SIRT3 inhibition, notably PGK1 and PGAM, highlights the critical role of acetylation in metabolic enzyme activity regulation, pointing to intricate regulatory networks modulating tumor cell metabolism." (PMID 38542426, 2024). "We observed a close relationship between different levels of PGK1 expression and tumor grade, vascular invasion, and lymph node metastasis in BLCA patients." (PMID 39315723, 2024). "Notably, proteins like Heat shock 70 kDa protein 1A/1B, Pyruvate kinase PKM, and Phosphoglycerate kinase 1 were suggested to be differentially regulated in OSCC patients, with implications for oral carcinogenesis and tumor growth." (PMID 39456901, 2024). "Increasing evidence has revealed that alteration in nutrition metabolism can lead to aberrant O-GlcNAcylation, which directly modifies metabolic enzymes such as PGK1, PFK1, G6PD, PKM2 and MDH1 to reprogram metabolic pathways, thereby contributing to tumor growth." (PMID 38778217, 2024). "In addition, albeit infrequently, tumor cells can also enhance glycolysis by upregulating the expression or activity of noncritical enzymes, such as phosphoglycerate mutase (PGM) and phosphoglycerate kinase 1(PGK1)." (PMID 38933335, 2024). "Besides the lipid phosphatase activity against PI3K/Akt signaling pathway, the protein phosphatase activity of PTEN against oncogenic factors such as the phosphoglycerate kinase 1 and the tyrosine kinase PTK6 also is essential in tumor suppression." (PMID 36774408, 2023). "Specifically, in HNSCC, PGK1 overexpression is frequently observed in primary tumours but not in healthy tissues, and elevated expression of PGK1 is significantly correlated with poor prognosis." (PMID 37723547, 2023). "In this study, we found that PGK1 may also be regulated by MAT, resulting in anti-tumor activity, which is rarely reported in MAT related studies." (PMID 37524857, 2023). "First, the exact relationship between the expression levels of PGK1 and the degree of tumour progression has not yet been established." (PMID 37723547, 2023).
tumor (continued). "In addition, the mechanism underlying PGK1-mediated tumour inhibition also includes the overexpression of PGK1 in Lewis lung cancer and the downregulation of COX-2 expression to reduce tumour growth in vivo." (PMID 37723547, 2023). "Additionally, PGK1 phosphorylates Beclin-1, which activates PI3K signaling pathway, conducing the tumor progression." (PMID 37449059, 2023). "Additionally, phosphoglycerate kinase 1 (PGK1) is upregulated in various types of BC, and it is a potential tumor promoting factor in BC." (PMID 36949536, 2023). "While the extracellular tumor-linked roles of PGAM1, LDHA, PKM, TPI1, and PGK1 have not been tested, the anti-tumor actions of ALDOA 13, 18, ENO1 16, 18, and GAPDH 20 were reported." (PMID 37056934, 2023). "Indeed, the GPx2 KD tumor expressed notably higher levels of glucose transporter GLUT1 (SLC2A1), aldolase-A (ALDOA), phosphoglycerate kinase (PGK1), and lactate dehydrogenase A (LDHA) than in the control tumor." (PMID 35193955, 2022). "Also, IL-6 through PGK1 phosphorylation in cancer cells and lncRNAs released from TAM increases tumor cell glycolysis and thereby boosts malignant progression." (PMID 36072596, 2022). "Generally, PGK1 protein level was closely related to tumor size and stage (P < 0.05), but not to age, gender and grade of KIRC patients." (PMID 35121728, 2022). "Moreover, in the tumor tissues, we used a co-immunoprecipitation assay to validate interactions between GARS and PGK1 as well as between GARS and PKM2." (PMID 35659036, 2022). "For instance, O-GlcNAcylation of PGK1 may coordinate glycolysis and TCA cycle to enhance tumor growth." (PMID 34790279, 2021). "ENO1, GCK, PGK1, and GAPDH are involved in tumor energy metabolism." (PMID 34194463, 2021). "For tumour cells also, a regulation of PGK1 function by specific non-coding RNAs, microRNAs (miRNAs) and long non-coding RNAs (LncRNAs), has been reported." (PMID 33234025, 2020). "To access whether the PGK1 overexpression in tumor tissues was related to cancer progression, we analyzed the TNM staging data of the 15 cancer types with significantly increased PGK1 mRNA levels." (PMID 31578148, 2019). "Apart from the PGK1-induced enhancement of energy supply, the mechanism might involve the stimulation of PGK1-activated oncogenic AKT/mTOR pathway in tumor cells." (PMID 29954422, 2018). "Cystatin-B (CSTB), leukotriene A-4 hydrolase (LTA4H), protein NDRG1 (NDRG1), and phosphoglycerate kinase 1 (PGK1) from the neoplastic island dataset and collagen alpha-1(VI) chain (COL6A1), integrin alpha-V (ITGAV) and myoglobin (MB) from the tumor stromal dataset were prioritized." (PMID 30185791, 2018). "Among them, 13 proteins correlated with clinicopathological parameters and of these proteins, eight proteins were identified in neoplastic islands (ACTR2, CSTB, COL1A2, LTA4H, PGK1, NDRG1, S100A8, S100A9) and five proteins were identified in tumor stroma (COL6A1, FSCN1, ITGAV, MB, THBS2)." (PMID 30185791, 2018). "However, the expression of glycolytic enzymes such as LDHA and PGK1 in the Myc signaling pathway was decreased in ACTH-PA, which was consistent with the reduced glycolysis observed in this tumor type." (PMID 30532734, 2018). "However, with this significant increase in the size cohort, LTA4H, PGK1, and ITGAV staining were identified with a slight variation within the lower and higher scores in each region, either ITF or inner tumor." (PMID 30185791, 2018). "PGK1 secreted by tumor cells inhibits angiogenesis and exerts a negative impact on tumor growth and metastasis." (PMID 30477236, 2018). "Moreover to further prove the effect of ACF on hypoxia-related proteins, VEGF, PGK-1 and HIF-1α mRNA levels were quantified in brain extracts from 9L tumor-bearing rats via RT-PCR." (PMID 29097800, 2017).
tumor (continued). "The hypoxia-Notch gene subset (HIF-1α/PGK1/VEGF/CA9/OPN-Notch1/Dll1/Hes1/Hes6/Hey1/Hey2) identified by us might hold prognostic implication and offer new opportunities in tumor sub-classification and targeted therapy." (PMID 25734817, 2015). "In this case of protein PGK1, the possible contribution of protein exportation cannot be completely ruled out, since it was reportedly to be secreted by tumor cells as a disulphide reductase." (PMID 18714357, 2008). "Here, in ESCC cells, we identified PGK1 promotes the transcriptional expression of c‐Myc by activating the β‐catenin signalling pathway, further enhancing the transcription of EMT and stemness‐related marker, thereby driving tumour cell progression and metastasis." (PMID 40534132, 2025). "Accordingly, we explored whether inhibiting the nonmetabolic activities of PGK1 could overcome radioresistance in PDAC using a subcutaneous tumor model in athymic nude mice." (PMID 41213904, 2025). "However, PGK1 plays a negative role in cancer progression by suppressing tumour growth in other types of cancer." (PMID 37723547, 2023). "In addition, polarized M2 macrophages produce IL-6 to promote the phosphorylation of the threonine 243 of phosphoglycerate kinase 1 (PGK1T243) mediated by 3-phosphoinositide-dependent protein kinase 1 (PDPK1) in tumor cells, promoting glycolysis and tumor progression." (PMID 35062950, 2022). "In line with this, the lactate levels increased both in tumor and peritumoral tissues, as well as the expression of glutamine transporters (i.e., SLC1A5) and glycolytic enzymes, such as glucose-6-phosphate isomerase (GPI), phosphoglycerate kinase (PGK1), aldolase A (ALDOA) and hexokinase 2 (HK2)." (PMID 33924061, 2021). "Moreover, the results revealed that the PGK1 expression had an evident negative correlation with tumor purity (p = 0.002) and a positive correlation with the immune score (p = 0.002), stromal score (p = 0.020), and ESTIMATE score (p = 0.002)." (PMID 34668665, 2021). "Using the integrated data of the tumor transcriptome from the TCGA database and the normal pancreas transcriptome from the Genotype-Tissue Expression (GTEx) database, we showed that LDHA, SLC2A1, and PGK1 were upregulated in tumor samples (logFC > 2, P < 0.05)." (PMID 33777046, 2021). "In PDA, PGK1 was not only more strongly expressed in > 70% of patients’ tumor tissues compared with nontumoral counterparts, but PGK1 levels in sera were also significantly higher in PDA patients compared to healthy controls, reflecting faster growth and more hypoxic tumors." (PMID 33804240, 2021). "Subsequently, PGK-1 (acting as a protein kinase) phosphorylates Beclin1 without affecting the formation of Beclin1/VPS34/ATG14L, which causes an altered conformation and increased activity of VPS34 as well as augmented autophagy for tumor homeostasis." (PMID 33256814, 2020). "High levels of R-2-HG also inhibit PHD (prolyl hydroxylases) and the degradation of HIF1-α, favoring tumor formation, growth and survival through the production of vascular endothelial growth factor (VEGF), glucose transporter 1 (GLUT1), phosphoglycerate kinase 1 (PGK1)." (PMID 30708988, 2019). "Thus, both PGK1 and CFL1 have some effects on tumor invasion, proliferation and metastasis, but whether they are associated with tumor cell radiosensibility remains unknown." (PMID 28903403, 2017). "However, whether PGK1 is related to the resistance of tumor cells to TKI drugs has not been reported." (PMID 35121728, 2022). "Phosphoglycerate kinase 1 (PGK1) serves as a critical metabolic enzyme in the process of glycolysis and has many nonmetabolic functions in tumour progression." (PMID 40534132, 2025). "In addition, AGR2 may also induce the expression of lactate dehydrogenase A (LDHA), phosphoglycerate kinase 1 (PGK1), kallikrein 2 (HK2) and enolase 1α (ENO1) through the MUC1/HIF-α pathway, thus induce glycolysis of cancer cells, promote cell proliferation, migration, invasion and tumor growth." (PMID 37197416, 2023).